HR (HR lysine demethylase and nuclear receptor corepressor)
Description:
Histone demethylase that specifically demethylates both mono- and dimethylated 'Lys-9' of histone H3. May act as a transcription regulator controlling hair biology (via targeting of collagens), neural activity, and cell cycle.
Synonyms: KDM3D; AU; ALUNC; HSA277165; HYPT4; MUHH; MUHH1
Tractability: PROTAC: ubiquitination databases record sites on it.
Gene: Protein-coding gene on chromosome 8 (22,114,419 to 22,133,384, reverse strand). Ensembl gene ENSG00000168453.
Subcellular location: Nucleus
Subcellular location (Human Protein Atlas): Nucleoplasm
Gene Ontology:
Molecular function: protein binding; transcription coregulator activity; histone H3K9 demethylase activity; histone H3K9me/H3K9me2 demethylase activity; transcription corepressor activity
Biological process: regulation of transcription by RNA polymerase II; chromatin remodeling; negative regulation of DNA-templated transcription
Cellular component: nucleoplasm; histone deacetylase complex; nuclear body; nucleus
Genetic constraint (gnomAD): Loss-of-function variants: 81 observed, 114.87 expected, observed/expected ratio (o/e) 0.71, 90% interval 0.59 to 0.85. The upper end of that interval is the gene's LOEUF score, 0.85, which puts it in group 3 of 6, group 1 being the genes least tolerant of losing a copy. Missense variants: 1,490 observed, 1,506.3 expected, observed/expected ratio (o/e) 0.99, 90% interval 0.95 to 1.03. Synonymous variants: 681 observed, 625.67 expected, observed/expected ratio (o/e) 1.09, 90% interval 1.02 to 1.16.
Homologues: Orthologues: chimpanzee HR (99% identical), macaque HR (90% identical), dog HR (84% identical), guinea pig HR (83% identical), mouse Hr (80% identical), pig HR (79% identical), rat Hr (79% identical), rabbit HR (77% identical), Drosophila melanogaster Kdm3 (16% identical). Paralogues in human: JMJD1C (28% identical), KDM3B (23% identical), KDM3A (20% identical).
Diseases named in the same sentence as HR in open-access papers:
HR is named in the same sentence as 59 diseases in open-access papers, as found by Europe PMC text mining. Sharing a sentence is not in itself a finding about the gene and the disease. The quoted sentences say what the papers report.
breast cancer (306 papers, 2015 to 2026). A primary or metastatic malignant neoplasm involving the breast. "This study examined 587 medical records of breast cancer (C50) patients, focusing on waiting times, treatment coordination, cancer characteristics, and diagnostic testing, with a specific emphasis on the HR+ HER- subtype." (PMID 40941615, 2025). "We identified 15,474 breast cancer-associated genes, emphasizing the HR+/HER2-subtype and the role of the tumor microenvironment in metastasis via STAT3 and p65 regulation." (PMID 40081286, 2025). "Bioinformatics analysis, integrating Gene Cards and GEO databases, 15,474 breast cancer-associated genes focusing on the HR+/HER2-subtype were identified." (PMID 40081286, 2025). "The SOLAR-1 trial led to the approval of alpelisib plus fulvestrant for patients with PIK3CA-mutated, HR+/HER2− advanced breast cancer." (PMID 41002573, 2025). "This case details the molecularly guided use of Fluzoparib plus Exemestane in a patient with HR+/HER2− advanced breast cancer and a gBRCA2 mutation, achieving remarkable long-term disease control." (PMID 41142243, 2025). "Although preclinical data supports its potent activity, real-world clinical evidence in advanced breast cancer, particularly combined with endocrine therapy in the HR+/HER2− gBRCA-mutated subtype, remains scarce." (PMID 41142243, 2025). "Following this, the American Food and Drug Administration and Health Canada approved the use of abemaciclib (CDK4/6 inhibitor) for patients with HR+/HER2− high-risk early breast cancer and a Ki-67 PI of ≥ 20%12." (PMID 38218973, 2024). "Alpelisib plus fulvestrant demonstrated a significant progression-free survival benefit versus fulvestrant in patients with PIK3CA-mutated HR+ /HER2− advanced breast cancer (ABC) (SOLAR-1)." (PMID 39177931, 2024). "The present analysis further characterizes the association between elevated inflammatory biomarkers and breast cancer relapse as being perhaps more relevant in subjects with HR+/HER2− tumors, and potentially less relevant in HER2+ tumors." (PMID 33483516, 2021). "Breast cancer patients diagnosed with HR+/HER2– tumors face a persistent risk of distant recurrence long after completion of their treatment." (PMID 34733416, 2021). "Firstly, we observed a significant reduction in the proliferation rate of the MCF7 breast cancer cell line (expressing HR+/HER2− phenotype), associated with a significant blockade of the cell cycle and low levels of apoptosis." (PMID 34770777, 2021). "That study found that Oncotype recurrence scores provide the risk of recurrence at 9 years in patients with HR+/HER2–/N0 breast cancer and identified the implications for various groups." (PMID 33194568, 2020). "PIK3CA mutation, which leads to increased PI3K activity, is the most common somatic mutation in breast cancer, and 36% of patients with HR+/HER2- breast cancer are PIK3CA mutated." (PMID 33489906, 2020). "According to previous research, the breast cancer subtype is an independent risk factor for the occurrence of metastasis, and the incidence of BM is highest in BC patients that are HR+/HER2− or HR+/HER2+." (PMID 33238981, 2020). "The third test, EndoPredict (Myriad Genetics, Salt Lake City, UT), is a 11-gene RT-PCR test that provides prognostic information regarding the risk of distant recurrence of breast cancer to patients with HR+ and HER2- tumors." (PMID 29796180, 2018). "Moreover, patients with triple-negative breast cancer (TNBC) were more likely to harbor BRCA1 mutations than those with HR+ or HER2+ breast cancer (P=0.006)." (PMID 35494038, 2022). "Future studies will determine if vitamin C can also improve the response of TNBC to other PI3K inhibitors, especially alpelisib, which was recently approved by the FDA to treat PIK3CA-mutated HR+/HER2- breast cancer and is under evaluation in ongoing TNBC clinical trials." (PMID 33664847, 2021). "PIK3CA mutations were identified in 36% of patients with HR+/HER2- breast cancer." (PMID 32326897, 2020).
breast cancer (continued). "We then assessed the use of adjuvant systemic therapy after limiting the cohort to those with HR+ /HER2− breast cancer given the small proportion of patients (6%) who had other subtypes." (PMID 41083834, 2026). "Despite the established role of NAC in breast cancer management, the therapeutic benefit remains markedly heterogeneous in patients with the HR+/HER2− subtype." (PMID 40936892, 2025). "Accordingly, the current real-world study aimed to explore the efficacy and safety of leuprorelin (Boennuokang®) plus endocrine therapy in premenopausal women with HR+/HER2− breast cancer." (PMID 40678728, 2025). "A first-in-human Phase I trial (NCT02792465) demonstrated that CFI-402257, either as monotherapy or in combination with Fulvestrant, exhibited a manageable safety profile in patients with solid tumors, including HR+/HER2– breast cancer." (PMID 40949156, 2025). "To evaluate the impact of continued CDK4/6i treatment in drug-resistant settings, we employed HR+/HER2− breast cancer cell lines (MCF-7, T47D, and CAMA-1) and a triple-negative breast cancer cell line (MDA-MB-231), all of which have an intact Rb/E2F pathway." (PMID 39605351, 2025). "Further, when HR+/HER2- breast cancer patients progress on endocrine therapy due to emergence of ESR1 resistance mutations, elacestrant therapy can significantly prolong PFS." (PMID 40711866, 2025). "The development of CDK4/6 inhibitors has revolutionized the treatment of HR+/HER2- advanced breast cancer." (PMID 39813224, 2025). "Three drugs (ribociclib, palbociclib, and abemaciclib) have been approved for the treatment of HR+/HER2– advanced-stage breast cancer in combination with ET." (PMID 39774684, 2025). "Abemaciclib is additionally indicated for the adjuvant treatment of HR+, HER2-, node-positive early-stage breast cancer at high risk of recurrence." (PMID 40136358, 2025). "A phase I/II trial has tested the safety and efficacy of palbociclib, pembrolizumab, and letrozole as a first-line treatment for HR+/HER2− advanced breast cancer patients." (PMID 41463246, 2025). "In conclusion, this study provides valuable insights into the management of breast cancer patients, including those with the HR+ HER- subtype." (PMID 40941615, 2025). "While CDK4/6 inhibitors (CDK4/6i) and endocrine therapy are standard-of-care for metastatic HR + /HER2- breast cancer, patient selection for durable efficacy remains undefined." (PMID 40506447, 2025). "The phase II GIADA trial (NCT04659551) enrolled patients with stage II-IIIA, LumB-like breast cancer (defined by HR+/HER2−, Ki67 ≥ 20%, and/or histologic grade 3)." (PMID 41465595, 2025). "This phase I/IIa study evaluated the safety, PK, pharmacodynamics, and preliminary antitumor activity of the first-in-class CDK2/4/6i PF-06873600, alone and in combination with ET, in patients with HR+/HER2− advanced breast cancer or mBC." (PMID 40243688, 2025). "CDK4/6 inhibitors such as palbociclib, ribociclib, and abemaciclib are approved by the Food and Drug Administration and European Medicines Agency for use in breast cancer (HR+/HER2−) when combined with hormonal therapeutics." (PMID 40642276, 2025). "Clinically, breast cancer is classified into three major subtypes: hormone receptor-positive (HR+), human epidermal growth factor receptor two-positive (HER2+), and triple-negative (TN) breast cancer." (PMID 40520159, 2025). "These tools have supported clinical decision making, particularly in HR+/HER2- breast cancer, and have been optimized over time." (PMID 41338056, 2025). "Based on in vivo and in vitro studies, we revealed that XBP1s enhanced the expression of E2F1 target genes by transcriptional activation of SND1, thereby exerting a pro‐survival effect in patients with HR+/HER2− breast cancer receiving the combined therapy." (PMID 40940685, 2025).
breast cancer (continued). "In line with these previous studies, we also discovered that E2, FSH, and LH were suppressed after leuprorelin (Boennuokang®) plus endocrine therapy in premenopausal women with HR+/HER2− breast cancer." (PMID 40678728, 2025). "Cyclin-dependent kinases 4 and 6 (CDK4/6) have emerged as crucial therapeutic targets in breast cancer treatment, particularly for hormone receptor-positive (HR+) and human epidermal growth factor receptor 2-negative (HER2-) subtypes." (PMID 39813224, 2025). "Maintaining E2 below 30 pg/mL indicates successful induction of a menopause-like state, which is related to better clinical outcomes in premenopausal women with HR+/HER2− breast cancer." (PMID 40678728, 2025). "HR+/HER2-breast cancer's progression is influenced by the tumour microenvironment (TME), which promotes cancer stem cell enrichment." (PMID 40081286, 2025). "In HR+/HER2-advanced breast cancer, the medical community has been exploring new therapeutic options for patients who develop resistance after CDK4/6 inhibitors combined with endocrine therapy." (PMID 39917165, 2025). "In this prospective study, we aimed to evaluate clinical, biological, and histopathological responses to NET in a cohort of postmenopausal patients with HR+/HER2− early-stage breast cancer." (PMID 40723203, 2025). "Specifically, it is projected that 66.2% of the 55,000 new breast cancer diagnoses anticipated in 2022 will involve patients with HR+ and HER2- tumors, equating to about 36,410 cases." (PMID 41089512, 2025). "Collectively, these findings underscore the role of KAT6B::ADK in enhancing the migratory and metastatic potential of HR+/HER2‒ breast cancer cells." (PMID 41213951, 2025). "The DESTINY-Breast, ASCENT, and TROPION trials enrolled distinct patient populations understudied with respect to the application of ADCs in the clinical setting—HER2-positive, triple-negative, and HR+/HER2− breast cancers, respectively." (PMID 41463194, 2025). "This prospective study confirms that neoadjuvant endocrine therapy (NET) with letrozole is a clinically effective and biologically meaningful strategy for tumor downstaging in postmenopausal patients with HR+/HER2− early breast cancer." (PMID 40723203, 2025). "One notable example is the RENATA study, which offers valuable insights into the real-world use of palbociclib in patients with HR+/HER2− advanced breast cancer, complementing the findings from randomised controlled trials (RCTs) such as PALOMA-2 and PALOMA-3." (PMID 40075608, 2025). "In conclusion, our findings confirm that NET with letrozole is a clinically and biologically effective strategy for tumor downstaging and biological modulation in postmenopausal patients with HR+/HER2− breast cancer." (PMID 40723203, 2025). "Abemaciclib, a drug approved for treating HR+/HER2− advanced breast cancer through CDK4/6 inhibition, significantly reduced the fluorescence intensity of GFP‐YAP1." (PMID 39968498, 2025). "TQB3909 is undergoing clinical evaluation in patients with HR+/HER2-advanced breast cancer (NCT05775575)." (PMID 40949156, 2025). "Current standard of care for patients with HR+/HER2− early breast cancer (EBC) includes adjuvant endocrine therapy with an aromatase inhibitor (AI) or tamoxifen (TAM)." (PMID 40153939, 2025). "In our external independent cohort, the number of patients who achieved pCR (n = 10) was relatively low, representing 9.43% of the total 106 HR+/HER2− breast cancer cases." (PMID 40936892, 2025). "In contrast, the single-arm phase II AVATAR trial that included only patients with hormone receptor-positive (HR+)/human epidermal growth factor receptor 2-negative (HER2-) advanced breast cancer demonstrated promising results." (PMID 40647452, 2025). "In our study, we observed that HR+/HER2‒ breast cancer patients harboring ADK fusions exhibited shorter RFS and OS as well as resistance to endocrine therapy." (PMID 41213951, 2025).
breast cancer (continued). "Due to similarities with our case, we highlight the case of a 36-year-old premenopausal Javanese woman with liver involvement and disseminated carcinomatosis of the bone marrow (DCBM) secondary to metastatic lobular hormone HR+/HER2-negative breast cancer." (PMID 41479780, 2025). "The phase III SONIA trial (NCT03425838) directly addressed this issue by comparing early (first-line) versus delayed (second-line) use of CDK4/6 inhibitors in patients with HR+/HER2− advanced breast cancer." (PMID 41383485, 2025). "According to the NCCN and ESMO clinical practice guidelines, OFS should be considered an adjunctive therapy in premenopausal women with HR+/HER2− breast cancer." (PMID 40678728, 2025). "The Artificial Intelligence Patient Librarian (AIPL) was designed to meet the psychosocial and supportive care needs of Metastatic Breast Cancer (MBC) patients with HR+/HER2− subtypes." (PMID 40136349, 2025). "We present the case of an elderly female patient with HR+/HER2-low advanced breast cancer complicated by significant pleural effusion." (PMID 41487578, 2025). "The AVATAR trial included only patients with HR+/HER2- breast cancer who had received one or two prior lines of therapy and were still considered to have estrogen-sensitive disease." (PMID 40647452, 2025). "For patients with HR+/HER2− advanced breast cancer, endocrine-based therapy remains the cornerstone of systemic treatment." (PMID 41445797, 2025). "A partitioned survival model was developed to compare costs and effectiveness of first-line (CDK4/6i-first) versus second-line (CDK4/6i-second) CDK4/6 inhibitor strategies among Chinese women with advanced HR+/HER2- breast cancer." (PMID 41383485, 2025). "We also observed a positive correlation between the expression of XBP1s and E2F1, as well as E2F1 targets in tumors obtained from patients with HR+/HER2− early breast cancer." (PMID 40940685, 2025). "In patients with PIK3CA-mutant, HR+/HER2– advanced breast cancer, the addition of inavolisib to palbociclib and fulvestrant substantially extended PFS to 17.2 months compared to 7.3 months with placebo." (PMID 40989687, 2025). "Gene expression profiles are used for decision making in the adjuvant setting in hormone receptor-positive, HER2-negative (HR+/HER2-) breast cancer." (PMID 40347583, 2025). "This multi-cohort phase II study evaluated the efficacy and safety of nivolumab combined with abemaciclib and fulvestrant or letrozole as a first-line/second-line treatment for HR+/HER2− advanced breast cancer." (PMID 41463246, 2025). "Following the distinction of molecular subtypes and the introduction of gene expression profiling and prognostic tools, chemotherapy is less frequently recommended for hormone receptor-positive, HER2-negative (HR+/HER2-) breast cancer." (PMID 41338056, 2025). "Based on its potent preclinical efficacy, PF-06873600 progressed to a first-in-human Phase 1/2a clinical trial in patients with advanced solid tumors, including HR+/HER2-breast cancer, TNBC, and ovarian cancer." (PMID 40949156, 2025). "The HR+ HER- subtype represents the most common breast cancer subtype in women diagnosed with early-stage breast cancer, as confirmed by our results, where stage IA was the most common." (PMID 40941615, 2025). "In 2015, the U.S. Food and Drug Administration (FDA) granted approval for palbociclib in combination with letrozole, a third-generation aromatase inhibitor, as first-line therapy for postmenopausal women with HR+/HER2-advanced breast cancer." (PMID 40520159, 2025). "Approximately 70 % of patients with advanced breast cancer have HR+, HER2− disease, and ET is an effective and standard first-line therapy for metastatic disease." (PMID 40161091, 2025). "Non-steroidal aromatase inhibitors, either alone or in combination with CDK4/6 inhibitors, are the first-line treatment options for human breast cancer (HR+/HER2−)." (PMID 40642276, 2025).